LINC02946 (long independently transcribed non-coding RNA 2946)
Synonyms: RMEL1
Gene: Long non-coding RNA gene on chromosome 2 (105,578,112 to 105,610,766, reverse strand). Ensembl gene ENSG00000287036.
Diseases named in the same sentence as LINC02946 in open-access papers:
LINC02946 is named in the same sentence as 5 diseases in open-access papers, as found by Europe PMC text mining. Sharing a sentence is not in itself a finding about the gene and the disease.
LINC02946 shares sentences with these, for which no sentence is quoted: melanoma (2 papers); glioblastoma (1); metastatic melanoma (1); metastatic tumors (1); tumor (1).